CCDC80 (coiled-coil domain containing 80)
Diseases named in the same sentence as CCDC80 in open-access papers (continued):
Sharing a sentence is not in itself a finding about the gene and the disease.
cancer (20 papers, 2010 to 2026). A tumor composed of atypical neoplastic, often pleomorphic cells that invade other tissues. "Remarkably, in cancer associated fibroblasts Dro1/Ccdc80 expression was highly down-regulated compared to normal intestinal stromal cells." (PMID 35422964, 2022). "Consistently, conditioned medium from Dro1/Ccdc80 deficient PSC from B16 xenograft tumors significantly inhibited caspase-3/7 activity in apoptosis induced B16 cancer cells." (PMID 35422964, 2022). "Since loss of host DRO1/CCDC80 strongly decreased cleavage of caspase-3 in B16 xenograft tumors, we investigated the effect of Dro1/Ccdc80 inactivation in stromal cells on apoptosis of B16 cancer cells in vitro." (PMID 35422964, 2022). "We conducted a pan-cancer analysis of CCDC80 expression using data from TCGA and the Genotype-Tissue Expression (GTEx) portal." (PMID 39308689, 2024). "Future studies are needed to further elucidate the role of Dro1/Ccdc80 in the apoptotic process during cancer development." (PMID 35422964, 2022). "Dro1/Ccdc80 suppresses anchorage independent growth, inhibits migration of cancer cells and induces sensitization to detachment-induced apoptosis." (PMID 35422964, 2022). "We performed KEGG pathway enrichment analysis and found that positive-related DEGs of CCDC80 were enriched in Ras signaling and proteoglycans in the cancer pathway." (PMID 34820451, 2021). "According to previous studies, CCDC80 is related to cancer cell motility in thyroid, colorectal, and pancreatic cancers." (PMID 32076068, 2020). "Regarding the three genes (WWOX, CADM1 and CCDC80) detected as SETDB2 target genes in our study, their loss or reduced expression has been reported in various cancers." (PMID 27572307, 2016). "Of implication to a role in cancer is the observation that mouse CCDC80 is involved in assembly of extracellular matrix and mediates cell adhesiveness." (PMID 20964819, 2010). "CCDC80 expression is closely related to patient prognosis in various malignant tumors." (PMID 39308689, 2024). "Interestingly, we also found strong upregulation of Cxcl15, Sfrp2, Dcn, and Ccdc80 genes when we compared TPC with KPC cancer cells." (PMID 37607005, 2023). "Future studies are required to further investigate Dro1/Ccdc80’s role in cancer stemness." (PMID 35422964, 2022). "Previously, we have found Dro1/Ccdc80 to sensitize cancer cells to various apoptotic stimuli." (PMID 35422964, 2022). "Through immunohistochemical staining of Ccdc80, we confirmed that the protein expression of Ccdc80 was significantly increased in the cancer tissues obtained from the vactosertib and Vac + nal-IRI/5-FU/LV-administered mice compared to the ones from the control and nal-IRI/5-FU/LV-administered mice." (PMID 32076068, 2020). "Thus, the expression of CCDC80 prevents cancer progression such as EMT." (PMID 34805166, 2021). "We then screened 12 hub genes from the blue module based on MM and GS, such as PODN, DCN, CCDC80, SVEP1 and AEBP1, which were reported to be predictive biomarkers and correlated with immune infiltration in various cancers." (PMID 36768989, 2023). "Moreover, the results of KEGG enrichment identified that CCDC80-related downregulated DEGs were enriched in the “Ras signaling pathway,” “Axon guidance,” and “Proteoglycans in cancer,” etc., while CCDC80-related upregulated DEGs may be involved in “DNA replication” and “Base excision repair,” etc.." (PMID 34820451, 2021). "In general, SRPX2 was reported as overexpressed in cancer while SRPX and CCDC80 were identified as downregulated in malignant conditions." (PMID 20964819, 2010). "It is known that WWOX and CADM1 but not CCDC80 have dense CpG islands in their promoter regions and hypermethylation at the promoter regions of WWOX and CADM1 has been reported in cancer cells." (PMID 27572307, 2016).
CCDC80 also shares sentences with these, for which no sentence is quoted: serous ovarian cancer (3 papers); cardiovascular diseases (2); Hepatic steatosis (2); adenocarcinoma (1); Amyloid (1); cardiomyopathy (1); cyst (1); dyslipidemia (1); endometriosis (1); gestational diabetes mellitus (1); glioblastoma (1); Insulin resistance (1); lung adenocarcinoma (1); muscular disorders (1); Myocardial fibrosis (1); Onset (1); Pan (1); Peripheral Nervous System Disease (1); prostate tumors (1); psoriasis (1); pulmonary hypertension (1); sarcoma (1); schistosomiasis (1); steatosis (1); stomach adenocarcinoma (1); Strabismus (1); systemic sclerosis (1); urinary system cancer (1).